TNNT2 (troponin T2, cardiac type)
Diseases named in the same sentence as TNNT2 in open-access papers (continued):
Sharing a sentence is not in itself a finding about the gene and the disease.
Becker muscular dystrophy (2 papers, 2023 to 2024). Becker muscular dystrophy (BMD) is a neuromuscular disease characterized by progressive muscle wasting and weakness due to degeneration of skeletal, smooth and cardiac muscle. "One patient was found to be heterozygous for a pathogenic variant in TNNT2 and, another patient was found to have an X-linked DMD variant that is associated with Becker Muscular Dystrophy." (PMID 39669619, 2024).
familial cardiomyopathies (2 papers, 2017 to 2021). "The cTnI and cTnT proteins are encoded by the TNNI3 and TNNT2 genes, respectively, and mutations in these genes are recognized as disease-causing mutations in patients with familial cardiomyopathies." (PMID 33961016, 2021).
left ventricular dilation (2 papers, 2015 to 2026). "In addition to the proband, the two siblings also carrying the R205Q TNNT2 mutation (one male, one female) showed evidence of marked left ventricular dilation (left ventricular internal diameter in diastole (LVIDd) of 4.4 – 6.6 cm) and reduced ejection fraction (13 – 47 %)." (PMID 26498512, 2015).
RASopathies (2 papers, 2021 to 2023). "In 15/16 cases, the RASopathy gene variant was the only LP/P variant identified, in one case two LP variants were seen; (RAF1 and TNNT2)." (PMID 33673806, 2021). "Due to the genetic heterogeneity of HCM, a comprehensive panel should be used for screening that covers not only the main sarcomeric culprits (e.g., TNNT2, MYH7, MYBPC3, TNNI3, ACTC), but also other causes including RASopathies, mitochondrial proteins, and glycogen storage diseases." (PMID 37180798, 2023).
sudden cardiac arrest (2 papers, 2021 to 2024). Unexpected rapid natural death due to cardiovascular collapse within one hour of initial symptoms. "Therefore, studying the effect of TNNT2 variants on cardiac propensity for arrhythmogenesis can pave the way for characterizing HCM in susceptible patients before sudden cardiac arrest occurs." (PMID 34977031, 2021).
ventricular tachycardia (2 papers, 2008 to 2021). A disorder characterized by an electrocardiographic finding of three or more consecutive complexes of ventricular origin with a rate greater than a certain threshold (100 or 120 beats per minute are commonly used). "The results of these studies are consistent with the high incidence of ventricular tachycardia and sudden cardiac death possibly linked to high Ca2+ sensitivity due to TNNT2 variants." (PMID 34977031, 2021). "Electrophysiological studies induced nonsustained ventricular tachycardia at low threshold in two of five Tnnt2+/−/TGK210Δ mice as contrasted with only one of 10 wildtype mice (p = 0.02)." (PMID 18612386, 2008).
atrial septal defect (1 paper, 2016). Interauricular communication is a congenital malformation characterized by a communication between the atrial chambers of the heart. "From these studies, we suggest TNNT2 is a gene worthy of screening for those with a congenital heart defect, particularly atrial septal defects and ventricular diverticula." (PMID 27194630, 2016).
Bradycardia (1 paper, 2025). A slower than normal heart rate (in adults, slower than 60 beats per minute). "To rule out the possible direct effect of dofetilide on endocardial cells independent of flow, we conditionally deleted Tnnt2 in the embryonic myocardium, which caused bradycardia in the E9.5 embryos and lethality at E10.5." (PMID 39932433, 2025).
Brugada syndrome (1 paper, 2018). A genetically heterogeneous condition characterized by complete or incomplete right bundle branch block accompanied by ST elevation in leads V1-V3. "As noted with TNNT2 previously, one gene (SCN5A) is associated with two different arrhythmogenic disorders: Brugada syndrome and LQT3." (PMID 30011878, 2018).
Co-infection (1 paper, 2025). "In our co-infection study, MYL3 and TNNT2 downregulation indicates the suppression of genes essential for striated muscle contraction." (PMID 40943072, 2025).
dilatation (1 paper, 2015). "In contrast, AAV9:Tnnt2-Cre treatment caused profound, rapidly progressive systolic dysfunction, ventricular dilatation, and death by 7 days post-injection." (PMID 26023924, 2015).
Down syndrome (1 paper, 2022). "Of note, increased DYRK1A expression in hearts from Ts65Dn mice, a mouse model of Down syndrome, impacts the splicing of TNNT2 and the relative proportions of cTnT transcript variants." (PMID 35596909, 2022). "We documented higher expression of fetal TNNT2 variants in myocardial tissue from donors with Down syndrome in comparison to samples from donors without Down syndrome." (PMID 35596909, 2022). "It is known that increased DYRK1A expression impacts the splicing of TNNT2 and the proportion of cTnT transcript variants in hearts from a mouse model of Down syndrome and in human non-cardiac cells." (PMID 35596909, 2022). "Phosphorylation of SRSF6 by DYRK1A promotes the inclusion of exon 5 into TNNT2 transcripts, and increased levels of phosphorylated SRSF6 were detected in myocardium from subjects with Down syndrome." (PMID 35596909, 2022). "Comparative analysis of the expression of the DYRK1A-SRSF6-TNNT2 pathway in myocardial tissue from individuals with and without Down syndrome revealed increased levels of phosphorylated SRSF6 and ~ 50% higher expression of fetal TNNT2 transcript variants in trisomic myocardium." (PMID 35596909, 2022).
inclusion body myositis (1 paper, 2019). A slowly progressive degenerative inflammatory disorder of skeletal muscles characterized by late onset weakness of specific muscles and distinctive histopathological features. "It has been reported that TNNT2 is re-expressed in diseased skeletal muscle from DM patients and from patients with other neuromuscular diseases such as inclusion body myositis (IBM)." (PMID 31611837, 2019).
large cell carcinoma (1 paper, 2022). A malignant epithelial neoplasm composed of large, atypical cells. "Immune checkpoint inhibitor was administered to 22 patients (5, squamous cell carcinoma; 16, adenocarcinoma; 1, large cell carcinoma) positive for TNNT2 protein in biopsy specimens." (PMID 35479276, 2022). "Immunoreactivity for TNNT2 protein was positive in 5, squamous cell carcinoma; 16, adenocarcinoma; 1, large cell carcinoma in 27 patients who received immune checkpoint inhibitors." (PMID 35479276, 2022).
Mitochondrial myopathy (1 paper, 2021). "Indeed, one term (GO:0033275) included three DEGs (ACTC1, MYL4, and TNNT2) with essential roles in muscle function, the former of which has also been shown to be overexpressed in mitochondrial myopathy due to mitochondrial respiratory chain deficiency." (PMID 34488775, 2021).
mucinous adenocarcinoma (1 paper, 2022). An invasive adenocarcinoma composed of malignant glandular cells which contain intracytoplasmic mucin. "TNNT2-positive non-mucinous adenocarcinomas exhibited the following histological grading: 0, well-differentiated; 8, moderately differentiated; 5, poorly differentiated." (PMID 35479276, 2022).
myofibrillar myopathy (1 paper, 2025). "Truncating variants in TTN are strongly associated with DCM, while mutations in DSP, LMNA, MYH7, RBM20, TNNT2, BAG3, and FLNC (the latter being linked to myofibrillar myopathy) are also commonly implicated." (PMID 39857686, 2025).
neuroendocrine carcinoma (1 paper, 2022). A malignant neuroendocrine neoplasm composed of cells containing secretory granules that stain positive for NSE and chromogranin. "This may be a potential reason why TNNT2 expression is not observed in neuroendocrine carcinomas." (PMID 35479276, 2022).
Noonan syndrome with multiple lentigines (1 paper, 2023). A rare multisystem genetic disorder characterized by lentigines, hypertrophic cardiomyopathy, short stature, pectus deformity, and dysmorphic facial features. "This is also the case for 8/14 syndromic HCM (CACNA1C, FLNC, PRKAG2, PTPN11 (Noonan), PTPN11 (Noonan syndrome with multiple lentigines), RAF1, RIT1, TTR), 3/12 DCM (DES, TNNC1 and TNNT2), and 2/6 ARVC (JUP, TMEM43) gene-disease pairs." (PMID 37872640, 2023).
squamous cell carcinoma (1 paper, 2022). A carcinoma arising from squamous epithelial cells. "Furthermore, TNNT2 mRNA was detected in the resected squamous cell carcinoma and adenocarcinoma tissues." (PMID 35479276, 2022). "In addition, TNNT2 was positively stained in 0, keratinizing; 1, non-keratinizing squamous cell carcinomas, meanwhile TNNT2 protein was negative in 5, keratinizing; 1, non-keratinizing ones." (PMID 35479276, 2022).
viral myocarditis (1 paper, 2021). Myocarditis that is caused by an infection with a viral agent. "Subsequently, we learned intermolecular interactions of herbal components and their targeting heart-tissue-specific CHRM2, FABP3, TNNC1, TNNI3, TNNT2, and SCN5A and cardiac-myocytes-specific IL6, MMP1, and PLAT coupled with viral myocarditis." (PMID 34456633, 2021).
cardiovascular disease (62 papers, 2012 to 2025). "Moreover, genes associated with human cardiovascular diseases, such as TNNT2, LMNA/C, TBX5, MYH7, ANKRD1, and NKX2.5, were also knocked-out by TALENs in human iPSCs to build cardiovascular disease models." (PMID 37626665, 2023). "Of the top 50 up-regulated hCM-specific genes we analyzed, 27 of them (54%) showed associations with at least one known cardiovascular diseases and 5 of them (NPPB, TNNT2, NPPA, RYR2, and PLN) were linked to more than 10 different types of cardiovascular diseases." (PMID 24474197, 2014).
cardiac disease (53 papers, 2009 to 2025). "For four of these loci, the top gene according to OPEN had been shown to be mutated in DCM (PLN, ACTN2, TNNT2, TTN), while for two others, the top gene was known to be mutated in HCM (MYL2) or an arrhythmogenic form of cardiac disease (CASQ2)." (PMID 25633252, 2014). "XIN deficiency might be a key mechanism of TNNT2-ΔK210 mutation-caused familial DCM and XIN could act as an interventional target for the relevant heart diseases." (PMID 34222259, 2021). "Several SFRP4-targeted genes, such as MYH6, MYH7, TNNT2 and NKX2-5, contributed to different types of heart diseases." (PMID 32423033, 2020).
cancer (36 papers, 2008 to 2026). A tumor composed of atypical neoplastic, often pleomorphic cells that invade other tissues. "Further analysis on cancer cell-specific genes revealed that KPmut-Late tumors exhibit elevated expression levels of several genes, including Prkg2, Hmga2, Wincr1, Cdkn2a, Tnnt2, Aqp5, and Sprr1." (PMID 37998349, 2023). "We are currently working the overexpression of TNNT2 in cancer cell lines on cellular kinetics and motility." (PMID 35479276, 2022). "qPCR was used to detect the mRNA expression of TNNT2 in cancer tissues and paraneoplastic tissue." (PMID 37481519, 2023). "The immunoreactivity for TNNT2 was localized in the nucleus, and this suggests that TNNT2 functions as a transcriptional factor in cancer cells, and might exert pro-metastatic and tumorigenic activity." (PMID 35479276, 2022). "Immunoreactivity for TNNT2 protein was localized in the cytoplasm and nucleus of cancer cells." (PMID 35479276, 2022). "The functional roles of TNNT2 in cancer cells remain unknown." (PMID 35479276, 2022). "We observed TNNT2 positive staining regardless of presence (+) or absence (-) of cardiovascular comorbidities (CVM): TNNT2(-)/CVM(-), 13; TNNT2(-)/CVM(+), 30; TNNT2(+)/CVM(-), 14; TNNT2(+)/CVM(+), 11 in 68 cancer patients." (PMID 35479276, 2022). "Furthermore, the genes encoding cTnC (TNNC1; Id: COSG56773), fsTnC (TNNC2; Id: COSG65631), and all three TnT isoforms (TNNT1, Id: COSG65275; TNNT2, Id: COSG67007; TNNT3, Id: COSG60869) are overexpressed in several cancer types according to the COSMIC database." (PMID 29416706, 2018).
infection (21 papers, 2009 to 2026). The state of being infected such as from the introduction of a foreign agent such as serum, vaccine, antigenic substance or organism. "Two days after infection, qRT-PCR analysis showed that total TNNT2 expression was reduced to 72.4 ± 3.1% of that in control cells." (PMID 38178244, 2024). "TNNT2 was also downregulated in the Tb single-infection group, possibly to reduce swimming performance, suggesting that suppression of this gene may be a general response to T. bryosalmonae infection." (PMID 40943072, 2025). "Consistent with GO based findings, the KEGG pathways analysis also revealed downregulation of contractile genes such as TNNT2 and MYL3, reinforcing infection-induced disruption of the muscular apparatus." (PMID 40943072, 2025).
myopathies (9 papers, 2012 to 2025). "Correspondingly, canonical MEF2 target genes linked to myopathy and contractile function, including TNNT2, MYH7, ACTN2, and ACTA1, were also restored upon HDAC5 silencing." (PMID 41283336, 2025).
tumor (9 papers, 2021 to 2026). "In addition, FCER2, CD200R1, and RHOV in the signature were strongly associated with the clinical stage of the tumor, and univariate cox analysis showed that except for TNNT2, WT1 and KRTAP5-8, the remaining signature genes were closely correlated with the prognosis of LUAD patients." (PMID 37234773, 2023). "It remains to be determined whether the cross-reactivity of TNNT2 protein between clonal expansion of a T-cell population activated by tumor cells and on cardiomyocytes is one of the putative mechanisms of myocardial toxicity in this study." (PMID 35479276, 2022). "In this case, myocardial injury was not manifested, and we found the immunoreactivity of TNNT2 in metastatic tumor cells." (PMID 35479276, 2022). "Interestingly, this cluster also has an elevated expression of MYH3, an embryonic form of myosin heavy chain, several cardiac cytoskeletal genes (ACTC1, TNNT2), and SERPINB9, which has previously been shown to protect tumor cells from granzyme B secreted by cytotoxic T lymphocytes." (PMID 41373578, 2025).
skeletal myopathies (8 papers, 2019 to 2025). "Mutations in the 3 TnT isoform genes (i.e., TNNT1, TNNT2, and TNNT3) have been found in cardiac and skeletal myopathies, suggesting that TnT plays a key role in striated muscle growth and function." (PMID 37186966, 2023).
neuromuscular disease (7 papers, 2019 to 2025). "It is known that TNNT2 alternative splicing is disrupted in DM and in other neuromuscular diseases such that exon 5 is inappropriately included in adult skeletal muscle." (PMID 31611837, 2019).
mitochondrial disease (1 paper, 2023). "Defects in sarcomere genes, such as MYH7, MYBPC3, TNNT2, TPM1, ACTC1, and TTN have been reported as causative for LVNC and LVNC is also commonly associated with mitochondrial diseases." (PMID 37186429, 2023).
TNNT2 also shares sentences with these, for which no sentence is quoted: diabetes (122 papers); Hypertension (88); coronary artery disease (76); acute myocardial infarction (68); Stroke (50); chronic kidney disease (47); atrial fibrillation (45); COVID-19 (40); ischemia (36); Renal insufficiency (27); Sepsis (27); renal dysfunction (24); angina (23); infarction (21); renal failure (21); congestive heart failure (20); pulmonary embolism (18); anemia (14); Myocardial necrosis (14); ischemic stroke (13); chronic obstructive pulmonary disease (12); kidney disease (12); Myocardial fibrosis (12); Obesity (12); breast carcinoma (11); hyperlipidemia (11); myositis (11); type 2 diabetes (11); atherosclerosis (10); injury (10).
A further 227 diseases each share a sentence with TNNT2 in 10 papers or fewer.